ZDHHC23 (zDHHC palmitoyltransferase 23)
Description:
Palmitoyltransferase that could catalyze the addition of palmitate onto various protein substrates and be involved in a variety of cellular processes (Probable). Palmitoyltransferase that mediates palmitoylation of KCNMA1, regulating localization of KCNMA1 to the plasma membrane. May be involved in NOS1 regulation and targeting to the synaptic membrane.
Synonyms: DHHC-23; MGC42530; NIDD
Tractability: Antibody: UniProt predicts a signal peptide or a membrane-spanning region.
Gene: Protein-coding gene on chromosome 3 (113,947,901 to 113,965,401, forward strand). Ensembl gene ENSG00000184307.
Subcellular location: Golgi apparatus membrane; Golgi apparatus, trans-Golgi network membrane
Subcellular location (Human Protein Atlas): Nucleoplasm
Gene Ontology:
Molecular function: protein binding; protein-cysteine S-palmitoyltransferase activity; palmitoyltransferase activity
Biological process: protein localization to plasma membrane; protein palmitoylation; protein targeting to membrane
Cellular component: endoplasmic reticulum; Golgi apparatus; Golgi membrane
Genetic constraint (gnomAD): Loss-of-function variants: 41 observed, 41.66 expected, observed/expected ratio (o/e) 0.98, 90% interval 0.77 to 1.28. The upper end of that interval is the gene's LOEUF score, 1.28, which puts it in group 5 of 6, group 1 being the genes least tolerant of losing a copy. Missense variants: 471 observed, 568.37 expected, observed/expected ratio (o/e) 0.83, 90% interval 0.77 to 0.89. Synonymous variants: 204 observed, 221.92 expected, observed/expected ratio (o/e) 0.92, 90% interval 0.82 to 1.03.
Homologues: Orthologues: macaque ZDHHC23 (96% identical), chimpanzee ZDHHC23 (93% identical), rabbit ZDHHC23 (91% identical), guinea pig ZDHHC23 (90% identical), pig ZDHHC23 (89% identical), rat Zdhhc23 (89% identical), mouse Zdhhc23 (88% identical), dog ZDHHC23 (84% identical), tropical clawed frog zdhhc23 (53% identical), zebrafish zdhhc23b (49% identical), zebrafish zdhhc23a (47% identical), Drosophila melanogaster GABPI (26% identical), and 3 more. Paralogues in human: ZDHHC4 (17% identical), ZDHHC1 (14% identical), ZDHHC14 (14% identical), ZDHHC7 (14% identical), ZDHHC3 (13% identical), ZDHHC18 (13% identical), ZDHHC11B (12% identical), ZDHHC11 (12% identical), ZDHHC12 (12% identical), ZDHHC20 (12% identical), ZDHHC21 (12% identical), ZDHHC6 (12% identical), and 5 more.
Diseases named in the same sentence as ZDHHC23 in open-access papers:
ZDHHC23 is named in the same sentence as 15 diseases in open-access papers, as found by Europe PMC text mining. Sharing a sentence is not in itself a finding about the gene and the disease. The quoted sentences say what the papers report.
glioma (6 papers, 2019 to 2023). A benign or malignant brain and spinal cord tumor that arises from glial cells (astrocytes, oligodendrocytes, ependymal cells). "It was found that ZDHHC5, ZDHHC17, ZDHHC18, and ZDHHC23 promote cellular self‐renewal by targeting glioma stem cells, which in turn induces malignant progression of tumor cells." (PMID 37434393, 2023). "Lastly, ZDHHC23 is known to serve as a potential therapeutic target for human gliomas, while its role in esophageal cancer is unclear." (PMID 36456979, 2022). "At present, it is only known that ZDHHC23 can target glioma stem cells of different glioblastoma subsets and regulate the cellular plasticity of these subsets." (PMID 34488541, 2021). "We then investigated the relationship between clinicopathological characteristics of patients and ZDHHC18 and ZDHHC23 expression levels in 90 glioma tissues." (PMID 30658672, 2019). "In these datasets, ZDHHC18 or ZDHHC23 was also found to be highly expressed in the GBM samples compared to that in the low-grade gliomas (LGGs) and normal brain tissues." (PMID 30658672, 2019). "Significant up-regulation of ZDHHC18 and ZDHHC23, especially the latter, was observed in a comparative analysis of 176 normal brain tissues and 2357 glioma tissues." (PMID 30658672, 2019). "In contrast, zDHHC23 is distributed at the border of human glioma tissue." (PMID 38293675, 2023). "zDHHC18 and zDHHC23 can target different subpopulations of glioma stem cells in specific settings." (PMID 38293675, 2023). "zDHHC18 is a mesenchymal glioma stem cell marker, whereas zDHHC23 is a glioma stem cell marker." (PMID 38293675, 2023). "Moreover, low level of ZDHHC23 was also associated with 1p/19q co-deletion (p < 0.01), loss of TERT (p < 0.05), and mutated ATRX (p < 0.01) in the glioma tumors." (PMID 30658672, 2019). "In addition, poor prognosis in patients with glioma associates with high co-expression levels of ZDHHC18 and ZDHHC23." (PMID 30658672, 2019). "ZDHHC18 and ZDHHC23 could target the glioma stem cells of different GBM subsets in the context of their specific niches and regulate the cellular plasticity of these subtypes." (PMID 30658672, 2019). "Herein, we studied the function of DHHC family proteins in gliomas and found that ZDHHC18 and ZDHHC23 are preferentially expressed in GBMs in comparison to LGGs." (PMID 30658672, 2019). "The prognostic value of ZDHHC18 and ZDHHC23 co-expression in the overall survival (OS) and disease free survival (DFS) of patients with glioma was examined using Kaplan–Meier survival curves." (PMID 30658672, 2019). "Thus, expression levels of ZDHHC18 and ZDHHC23 were positively correlated with the increasing tumor grade, both in the publicly available databases and in our cohort of primary tumor specimens, and might, therefore, constitute novel prognostic biomarkers for gliomas." (PMID 30658672, 2019).
breast carcinoma (2 papers, 2016 to 2022). "We found that IL1R1 (Il1r1 interleukin 1 receptor, type I), BCAR3 (breast cancer anti-estrogen resistance 3), KCNH2 (potassium channel, voltage gated related subfamily H, member 2), PIR (pirin), and ZDHHC23 (zinc finger, DHHC-type containing 23) were differentially expressed." (PMID 27536776, 2016).
glioblastoma (2 papers, 2019 to 2021). The most malignant astrocytic tumor (WHO grade IV). "The different anatomical regions of glioblastoma were analyzed by immunofluorescence using antibodies against ZDHHC18 and ZDHHC23, which demonstrated that both ZDHHC18 and ZDHHC23 were mostly localized in the nucleus and cytoplasmic vesicles around the nucleus." (PMID 30658672, 2019).
astrocytoma (1 paper, 2017). "Moreover, high expression of 7 of the high-malignant genes (C7ORF46, DUSP4, HS3ST3B1, ODZ1, TTL, VAV3, ZDHHC23) or low expression of 4 of the low-malignant genes (AKR1C3, ARHGEF10L, SMAD7, ST3GAL6) was associated with a lower progression free survival probability of grade III astrocytoma patients." (PMID 29152145, 2017).
esophageal cancer (1 paper, 2022). A primary or metastatic malignant neoplasm involving the esophagus. "Collectively, findings obtained in the current in silico study provide evidence for the prognostic evaluation in esophageal cancer following radiotherapy by targeting the miR-132-3p/CAND1/ZDHHC23 and miR-576-5p/AHR pathways." (PMID 36456979, 2022). "Our study demonstrated that miR-132-3p/CAND1/ZDHHC23 and miR-576-5p/AHR were critical molecular pathways related to the radiosensitivity of esophageal cancer." (PMID 36456979, 2022). "The prognostic risk model based on 2 miRNAs (miR-132-3p and miR-576-5p) and 4 mRNAs (CAND1, ZDHHC23, AHR, and MTMR4) could accurately predict the prognosis of esophageal cancer patients." (PMID 36456979, 2022). "Altogether, the miR-132-3p/CAND1/ZDHHC23 and miR-576-5p/AHR pathways could affect radiosensitivity in esophageal cancer." (PMID 36456979, 2022). "Additionally, our findings indicated that the miR-132-3p/CAND1/ZDHHC23 and miR-576-5p/AHR pathways could influence radiosensitivity in esophageal cancer." (PMID 36456979, 2022). "Finally, it was verified that miR-132-3p/CAND1/ZDHHC23 and miR-576-5p/AHR could affect the radiosensitivity in esophageal cancer." (PMID 36456979, 2022). "Ultimately, 2 miRNAs (namely, miR-132-3p and miR-576-5p) and 4 mRNAs (namely, CAND1, ZDHHC23, AHR, and MTMR4) were obtained followed bioinformatics analyses, and possessed the potential to serve as prognostic biomarkers for radiosensitivity in esophageal cancer patients." (PMID 36456979, 2022). "Furthermore, we uncovered that the prognostic risk model based on 2 miRNAs (miR-132-3p and miR-576-5p) and 4 mRNAs (CAND1, ZDHHC23, AHR, and MTMR4) could accurately and effectively predict the prognosis of patients with esophageal cancer." (PMID 36456979, 2022).
tumor (4 papers, 2019 to 2023). "The ZDHHC18 expression level was increased in perinecrotic and microvascular proliferative regions, and that of ZDHHC23 was associated with the leading edge and infiltrating tumor regions in GBM." (PMID 30658672, 2019). "The high levels of expression of ZDHHC18 and ZDHHC23 were related to the tumor grade (IV, p < 0.01 for ZDHHC18; IV, p < 0.01 for ZDHHC23)." (PMID 30658672, 2019). "From the UALCAN web resources based on TCGA datasets, ZDHHC23 expression was positively correlated with the HCC stage and tumor grade." (PMID 37828054, 2023).
cancer (3 papers, 2023 to 2025). A tumor composed of atypical neoplastic, often pleomorphic cells that invade other tissues. "Similarly, palmitoyl-acyltransferase ZDHHC23 displayed a positive association with DNA damage and mTOR pathways in eight and three cancer types, respectively." (PMID 37978524, 2023). "Immunohistochemical analysis of liver tissues from HCC patients revealed higher ZDHHC23 and SREBP1c expression and lower PHF2 expression in cancer tissues than in adjacent normal tissues." (PMID 37828054, 2023).
ZDHHC23 also shares sentences with these, for which no sentence is quoted: colon cancer (1 paper); endometrial cancer (1); epilepsy (1); infection (1); liver cancer (1); pancreatic cancer (1); renal carcinoma (1); thyroid cancer (1).